RBM3 (RNA binding motif protein 3)
Diseases named in the same sentence as RBM3 in open-access papers (continued):
Sharing a sentence is not in itself a finding about the gene and the disease.
cancer (continued). "In high-grade T24 carcinoma cells, which expressed higher RBM3 mRNA levels compared to RT4 cells, RBM3 silencing conferred a decreased sensitivity to cisplatin and gemcitabine." (PMID 35109796, 2022). "High RBM3 protein expression has been reported as a favorable prognostic marker in several types of cancer, recently also in NSCLC." (PMID 32491279, 2020). "High expression of the RNA‐binding motif protein 3 (RBM3) correlates with improved prognosis in several major types of cancer." (PMID 32491279, 2020). "Other studies also suggest that RBM3 plays an important role in the proliferation of cancer cells, fibroblasts, and HEK293 cells." (PMID 31824945, 2019). "This would help explain the large number of reports linking high RBM3 expression to reduced metastasis and better clinical outcome across many cancers." (PMID 29743635, 2018). "Using immunohistochemistry, dysregulated RBM3 expression has been suggested as prognostic biomarker in several cancers." (PMID 30419865, 2018). "Our finding that RBM3 promotes cell migration – a property that would be expected to enhance cancer metastasis – appears to be at odds with numerous reports that high RBM3 expression limits cancer progression." (PMID 29743635, 2018). "A potential explanation for this discrepancy is that high RBM3 expression in general (which is more easily detected and quantified in nuclei, as opposed to cell protrusions, in histological sections) restricts cancer cells to a mesenchymal mode of migration." (PMID 29743635, 2018). "The comparative analysis of normal and neoplastic epithelium revealed that RBM3 expression was reduced in a fraction of cancers." (PMID 30419865, 2018). "An increase of RBM3 in malignant relative to corresponding benign tissue has been suggested in gastric, prostate and breast cancer." (PMID 30419865, 2018). "A clearer picture of RBM3’s role in cancer will require an understanding of the composite influence of RBM3’s varied molecular functions." (PMID 29743635, 2018). "Compared with a normal oral epithelium, human papillomaviruses-oropharyngeal carcinomas exhibit reduced RBM3 expression, but a potential biomarker for this of type cancer should be further pursued." (PMID 28118608, 2017). "In the present review, we provide an overview of current knowledge concerning the role of RBM3 in various cancers and neuroprotection." (PMID 28118608, 2017). "For instance, RBM3 has been noted high expression in various cancers and then featured as a potential proto-oncogene." (PMID 28118608, 2017). "The Human Protein Atlas (HPA) project (proteinatlas.org), an excellent tool for new biomarker discovery, has already featured RBM3 as a potential biomarker in cancers." (PMID 28118608, 2017). "The roles of other RBPs in cancer have been elucidated, but the literature concerning the exact mechanisms of RBM3 in cancer are conflicting." (PMID 28118608, 2017). "Whereas both proteins are generally upregulated in cancer tissues compared with normal tissue, RBM3 has been identified unanimously as a biomarker for favorable outcome; CIRP for poor outcome." (PMID 27147467, 2016). "Specific cancer types likely differentially affect RBM3 signaling as is known for other proteins, such as estrogen receptors." (PMID 27147467, 2016). "The hypoxic cancer stem cell niche provides a microenvironment for the maintenance of immature cancer cells, and moderates hypoxia triggers the induction of RBM3." (PMID 27147467, 2016). "Kaplan-Meier analysis was used to assess the impact of RBM3 expression on cancer-specific survival (CSS) and failure-free survival (FFS)." (PMID 25811459, 2015). "Expression of the RNA-binding motif protein 3 (RBM3) has been shown to correlate with favourable clinicopathological parameters and prognosis in several cancer diseases." (PMID 25811459, 2015).
cancer (continued). "Increased expression of RBM3 has been noted in several cancer cell types where it has been proposed to act as a protooncogene that facilitates cell division and attenuates apoptosis." (PMID 22145045, 2011). "RBM3 is also induced by other physiological stressors, and is upregulated in various cancer types and degenerative states, potentially coupling these conditions to changes in miRNA expression." (PMID 22145045, 2011). "It is evident that RBM3, while sparsely expressed in normal tissue, is up-regulated in most cancer forms and their pre-invasive stages in vivo." (PMID 21955582, 2011). "RBM3, a cold-induced RNA-binding protein, was found to be upregulated in several types of cancers." (PMID 34804951, 2021). "In addition, RBM3, an RNA-binding protein, has been shown to function as an oncogene in many cancers and promote YAP mRNA stability." (PMID 33330099, 2020). "However, RBM3 was previously found to be induced by moderate (5%) and severe (1%) hypoxia in HeLa and Hep3B cancer cells." (PMID 31824945, 2019). "Do the morphoregulatory functions of RBM3 inform on its role in cancer and utility as a biomarker?" (PMID 29743635, 2018). "RBM3 expression has been suggested as prognostic marker in several cancer types." (PMID 30419865, 2018). "Cancers with high nuclear RBM3 might adopt this status as a result changes in nucleocytoplasmic transport that shunt RBM3 away from cell protrusions where it would otherwise enhance mesenchymal migration." (PMID 29743635, 2018). "If so, then the metastasis of cancers that rely on MAT-AMT flexibility for migration might be hindered by upregulation RBM3." (PMID 29743635, 2018). "In cancer there are multiple contradictory reports regarding the role and expression of RBM3." (PMID 30419865, 2018). "The partial mechanism for RBM3 overexpression may involve in increasing β-catenin signaling, a pathway that enhances cancer stemness." (PMID 28118608, 2017). "High level RBM3 protects cancer cells from mitotic catastrophe or apoptosis." (PMID 28118608, 2017). "In addition to the roles of RBM3 in cancer, increasing evidence has described its neuroprotective functions, as demonstrated by five aspects." (PMID 28118608, 2017). "Thus, it can be assumed that the exact role of RBM3 in cancers is largely dependent on the cancer type and the molecular context activated in different pathways." (PMID 28118608, 2017). "Therefore, in this review, we mainly focus on the functions of RBM3 in cancers and neurodegenerative diseases." (PMID 28118608, 2017). "It is evident that RBM3 is up-regulated in various types of human malignancies and in vitro studies in a wide range of different model systems have demonstrated that RBM3 is involved in multiple processes central to cancer biology, like proliferation, apoptosis and angiogenesis." (PMID 21777469, 2011). "However, there is also emerging evidence that very high expression of RBM3 within the nuclear compartment in some cancer types is a positive predictor of clinical outcome." (PMID 22145045, 2011). "Considering the potentially important roles of Cirbp and Rbm3 in hyperthermia for cancer therapy, we first examined the effects of hyperthermia treatment on the expression of thermomiRs (i.e., miR-142-5p and miR-143) (used as positive control), and Cirbp and Rbm3 by qRT-PCR." (PMID 38419081, 2024). "In light of such data, the presence of RBM3 in SICs and invasive filopodia suggests that it has morphoregulatory functions in cell shape and migration, which may be important to its stress response functions and putative involvement in development and cancer." (PMID 29743635, 2018). "Importantly, the role of RBM3 in different cancers remains contested." (PMID 28118608, 2017). "Thus, RBM3 appears to increase cell survival and proliferation, particularly in specific adverse growth conditions, and appears to be driving oncogenesis in various cancers." (PMID 26577765, 2015).
cancer (continued). "It is reasonable to speculate, then, that the pro-survival functions of RBM3 in cancer cells, and the therapeutic effects of downregulating RBM3 by heat shock, may involve its activity on miRNAs that have previously been linked to oncogenesis (e.g. the miR-17-92 cluster)." (PMID 22145045, 2011). "Kaplan-Meier and Cox regression analyses were applied to estimate the impact of RBM3 expression on time to recurrence (TTR), cancer-specific survival (CSS), and overall survival (OS) in strata according to NAC treatment." (PMID 35109796, 2022). "Going through the list of the top 20 up- and downregulated DEGs, RBM3 appeared as the most significant upregulated DEG; this gene, being a cancer biomarker, is also shown to promote DNA integrity and promote cellular homeostasis through complex signaling." (PMID 35563749, 2022). "RNA-binding motif protein 3 (RBM3) has previously been shown to be an independent prognostic and predictive biomarker in several types of cancer." (PMID 29464064, 2018). "The RNA-binding motif protein 3 (RBM3) is a cold-inducible RNA-binding protein with broadly relevant roles in cellular protection, and putative functions in cancer and development." (PMID 29743635, 2018). "Using tissue microarrays and immunohistochemistry, PODXL and RBM3 expression was evaluated in 272 incident UBC cases from the prospective, population-based cohort study Malmö Diet and Cancer." (PMID 28293425, 2017). "RBM3 can bind to and alter the translation of mRNA, as shown for COX-2, IL-8, and vascular endothelial growth factor (VEGF) in macrophages or cancer cells, presumably in a cell type-specific manner and involving the interaction with HuR." (PMID 27147467, 2016). "In the present series, low expression of RBM3 was a predictor for increased risk of treatment failure in patients with metastatic NSGCT, and one could hypothesize that RBM3 may be a predictor of sensitivity to cisplatin-based treatment also in this type of cancer." (PMID 25811459, 2015). "High nuclear expression of the RNA-binding motif protein 3 (RBM3) has previously been found to correlate with favourable clinicopathological characteristics and a prolonged survival in several cancer forms." (PMID 24963396, 2014). "Yet, as a consequence of the observation that RBM3 seems to be necessary for the maintenance of cellular integrity during various stress conditions, it has been hypothesized that targeting RBM3 could prove to be an efficient novel therapeutic strategy against cancer." (PMID 20727170, 2010). "Among these genes, ANXA2R (Annexin A2 Receptor), RBM3 (RNA-binding Protein 3), and SUCLG2 (Succinyl-CoA ligase [GDP-forming] subunit β), which may act as cancer drivers, were downregulated." (PMID 39766901, 2024). "Supporting this notion, RBM3 is known to be up-regulated in non-malignant proliferating cells and cancer." (PMID 29464064, 2018). "The metastasis of many cancers is facilitated by migration mode flexibility – i.e. the ability to undergo MAT and AMT transitions – and we hypothesize that high RBM3 expression impairs this flexibility by “locking” cells into a mesenchymal mode." (PMID 29743635, 2018). "A common observation in human tissue is that RBM3 is up-regulated in cancer and in proliferating non-malignant cells, compared to normal cells." (PMID 20727170, 2010). "Cold shock proteins such as the RNA-binding protein RBM3 and cold-inducible RNA-binding protein (CIRBP) are involved in diverse physiological and pathological processes, including circadian rhythm, inflammation, neural plasticity, stem cell properties, and cancer development." (PMID 40152901, 2025). "Moreover, it has been demonstrated that reduction of RBM3 expression – and expression of the highly homologous cold-inducible RNA binding protein (CIRP) – by heat shock impairs the survival of cancer cells and increases their sensitivity to chemotherapeutic compounds." (PMID 22145045, 2011).
cancer (continued). "Insofar as RBM3 knockdown appeared to recapitulate several aspects of MAT exhibited by mesenchymal cancer cells, our data may also help inform on the mechanistic significance of correlations between RBM3 expression level and both the metastatic potential and clinical outcome of many cancers." (PMID 29743635, 2018).
neurodegenerative disease (10 papers, 2017 to 2022). A disorder of the central nervous system characterized by gradual and progressive loss of neural tissue and neurologic function. "Specifically, it is possible that the loss of RBM3 function leads to or aggravates neurodegenerative diseases." (PMID 29773975, 2018). "Alternatively, RBM3 can be targeted as a diagnostic biomarker for patients with neurodegenerative diseases." (PMID 28118608, 2017). "In conclusion, early synapse loss in mouse models of neurodegenerative diseases that results from defective synaptic repair processes is associated with failure to induce RBM3 protein expression." (PMID 28118608, 2017). "Furthermore, we showed that failure to induce RBM3 expression underlies the impaired synapse regenerative capacity underlying the earliest stages of synapse loss in several mouse models of neurodegenerative disease." (PMID 33563652, 2021). "Cold-shock proteins such as RNA-binding motif protein 3, RBM3, are essential for maintaining synapses in laboratory mouse models of neurodegenerative diseases." (PMID 35821840, 2022). "Rbm3 over-expression resulted in sustained synaptic protection in mouse models of neurodegenerative disease, eliminating behavioral deficits and cell degradation, thereby increasing the survival time." (PMID 33546359, 2021). "RBM3 plays a crucial role in mediating synaptic plasticity essential for neuroprotection in mouse models of neurodegenerative disease." (PMID 32648620, 2020). "Our data suggest that RBM3 induction or overexpression is a potential strategy for therapy of neurodegenerative diseases such as PD." (PMID 29773975, 2018). "In mouse models of degenerative diseases, RBM3 was found to mediate structural plasticity and protective effects of cooling against neuron loss." (PMID 29773975, 2018). "In the future, a MPTP-based PD mouse model should be used to determine the actual role of RBM3 in neurodegenerative diseases." (PMID 29773975, 2018). "We recently showed that the cold shock RNA-binding protein, RBM3, plays a critical role in mediating synaptic repair processes essential for neuroprotection in mouse models of neurodegenerative disease." (PMID 28238655, 2017). "In neurodegenerative diseases and brain injury models, high RBM3 expression is also involved in neuroprotection." (PMID 28118608, 2017). "Thus, the therapeutic induction of RBM3 is an appealing novel target for neurodegenerative diseases." (PMID 33563652, 2021). "However, under pathological conditions such as neurodegenerative disease, RBM3 acts as a stress-response protein, significantly influencing neural survival and function." (PMID 31484925, 2019). "Another question has also been raised about the role of RBM3 in neurodegenerative diseases." (PMID 29773975, 2018). "Finally, in neurodegenerative diseases, RBM3 exerts a neuroprotective function via structural plasticity, a process wherein synapses are continuously remodeled by dismantling and reassembling processes in healthy adult brain." (PMID 28118608, 2017). "Inducing RBM3 specifically in injured brain areas may be a promising therapy for neurodegenerative diseases." (PMID 28134320, 2017). "Finally, we show that the marked neuroprotective effects of cooling in prion-diseased mice are abolished by pharmacological inhibition of the pathway by preventing RBM3 induction, highlighting its relevance as a novel target for therapeutic modulation for neurodegenerative diseases." (PMID 33563652, 2021). "Recently, the cold-shock protein, RBM3, an RNA chaperone highly expressed in neurons, has been shown to be the principal mediator of cold-induced neuroprotection in several mouse models of neurodegenerative disease, through its effects on structural synaptic plasticity and synapse regeneration." (PMID 33563652, 2021).
neurodegenerative disease (continued). "Finally, we show that RTN3 expression, downstream of RBM3 induction, mediates cooling-induced neuroprotection in mice with neurodegenerative disease and importantly is neuroprotective even in the absence of cooling." (PMID 28238655, 2017). "Our data thus far predict that activation of TrkB alone, in the absence of cooling should induce the cold-shock proteins, RBM3 and RTN3, and confer neuroprotection in the context of neurodegenerative disease." (PMID 33563652, 2021). "A possible reason is that RBM3 induction by hypothermia in MPP+ model is not enough to rescue apoptosis induced by MPP+14 In the future, MPTP‐ and ROT‐based PD mouse model should be used to determine the actual role of hypothermia in neurodegenerative diseases such as PD." (PMID 31436914, 2019).
adenocarcinoma (3 papers, 2013 to 2020). A common cancer characterized by the presence of malignant glandular cells. "Cases with high nuclear RBM3 protein expression had a prolonged 5‐year OS in both cohorts when analyzing adenocarcinomas separately (P = .02 and P = .01)." (PMID 32491279, 2020). "The results from this study demonstrate that reduced RBM3 expression is an independent factor of a shorter overall and recurrence free survival in patients with adenocarcinoma of the upper gastrointestinal tract." (PMID 24963396, 2014). "Immunohistochemical RBM3 expression was analysed in tissue microarrays with primary radiotherapy- and chemotherapy-naive adenocarcinoma of the esophagus, gastroesophageal junction and stomach (n = 173)." (PMID 24963396, 2014). "In conclusion, the results from this study demonstrate that reduced RBM3 expression is an independent factor of poor prognosis in patients with adenocarcinoma of the upper gastrointestinal tract." (PMID 24963396, 2014). "Therefore, in this study, the expression and prognostic impact of RBM3 was examined in a consecutive cohort of radiotherapy- and chemotherapy-naive adenocarcinoma of the esophagus and stomach (n = 173)." (PMID 24963396, 2014).
infection (2 papers, 2019 to 2021). The state of being infected such as from the introduction of a foreign agent such as serum, vaccine, antigenic substance or organism. "Thus, increased temperature, not infection or inflammation, mediated decreased RBM3 levels." (PMID 30802174, 2019).
brain disorder (1 paper, 2019). A disease affecting the brain or part of the brain. "Although the underlying mechanisms remain largely unknown, this suggests that RBM3-targeted therapy could be safe to administer in brain disorders." (PMID 31484925, 2019).
RBM3 also shares sentences with these, for which no sentence is quoted: prostate tumor (2 papers); testicular non-seminomatous germ cell cancer (2); age (1); amyotrophic lateral sclerosis (1); asphyxia (1); bipolar disorder (1); cancer of the digestive system (1); cardiovascular disease (1); Cluster headache (1); COVID-19 (1); dementia (1); diabetic kidney disease (1); endometrial cancer (1); endometrioid carcinoma (1); epilepsy (1); Huntington disease (1); hypertrophy (1); in liposarcoma (1); inflammation (1); Insulin resistance (1); lymph node metastases (1); medulloblastoma (1); metastatic cancer (1); mucinous carcinoma (1); neurological disorders (1); ovarian tumors (1); preeclampsia (1); PRLomas (1); prostatic (1); rheumatoid arthritis (1).
A further 8 diseases each share a sentence with RBM3 in 1 paper.